HNRNPA2B1 (heterogeneous nuclear ribonucleoprotein A2/B1)
Diseases named in the same sentence as HNRNPA2B1 in open-access papers (continued):
Sharing a sentence is not in itself a finding about the gene and the disease.
cancer (continued). "HNRNPA2B1 levels have been associated with the survival rates of patients with cancer." (PMID 35529270, 2022). "hnRNPA2B1 is implicated to play a direct role in cancer development, progression, gene expression, and signal transduction and has been proposed to account for the oncogenic effects of several types of cancers." (PMID 33163396, 2020). "This affected 17/333 pathway-associated genes including six known cancer genes (HNRNPA2B1, STAG2, TCF7L2, SUZ12, CLTC, and ZNF521), Thus, the integration procedure prioritized specific pathway-related genes compared to their original rankings in individual mutation datasets." (PMID 32024846, 2020). "Thus, this study assessed whether HNRNPA2B1 levels are associated with genetic alterations and immune cell infiltration in pan-cancer." (PMID 35529270, 2022). "Functional analyses across multiple EBV+ cancer cell models demonstrated that HNRNPA2B1 acts as a restriction factor for EBV lytic reactivation." (PMID 42283463, 2026). "The m6A mRNA reader hnRNPA2B1 enhances the stability of oncogenic mRNAs in an m6A-dependent manner, promoting the progression of cancer." (PMID 39964621, 2025). "Among these readers, heterogeneous nuclear ribonucleoprotein A2B1 (hnRNPA2B1) presents an important role across various cancers." (PMID 41271615, 2025). "hnRNPA2B1 is acknowledged as a critical oncogenic driver in various cancers including but not limited to multiple myeloma, breast cancer, and non‐small‐cell lung cancer." (PMID 39810713, 2025). "A few genes, such as TRUB2 and HNRNPA2B1, are consistently expressed across most cancer types, primarily due to their involvement in fundamental biological processes or their roles in large biomolecular complexes." (PMID 40867324, 2025). "Previous studies have identified HnRNPA2B1 as an m6A reader, highlighting its potential key role in regulating the progression of various cancers." (PMID 40770637, 2025). "The results were consistent with those for OS and DSS, suggesting that HNRNPA2B1 is a potential pan-cancer prognostic biomarker." (PMID 39268079, 2024). "Prospective studies on the expression of HNRNPA2B1 and its role in immune infiltration of human cancers are needed next, as well as the successful development and testing of novel antitumor immunotherapeutic agents targeting HNRNPA2B1." (PMID 39268079, 2024). "Building on this, we further analyzed the potential applications of HNRNPA2B1 expression levels across different cancers." (PMID 39268079, 2024). "In our study, we analyzed the expression of HNRNPA2B1 in various types of cancer and its relationship with patient prognosis." (PMID 39268079, 2024). "DFS analysis observed that high expression of HNRNPA2B1 in three cancers resulted in cancer progression, including CESC, LIHC, ACC, and low expression of HNRNPA2B1 in OV with cancer progression." (PMID 39268079, 2024). "We checked the candidates one by one in these three listed results and reviewed previous research, finding that hnRNPA2B1, which increases telomerase activity and telomere length in cancer cells, appeared in ranks of the list of these proteins." (PMID 39187478, 2024). "We used Cox regression analysis to analyze the prognostic relationship between HNRNPA2B1 expression and all types of cancer, and statistical tests using logrank test to get prognostic significance." (PMID 39268079, 2024). "Analysis of HNRNPA1B1 expression in different clinical stages of cancers confirmed that HNRNPA2B1 plays an important role in the progression of LUSC, LIHC, TGCT, ACC, CESC, OV, KIPAN, and LUAD." (PMID 39268079, 2024). "After applying the CIBERSOR method to assess the immune cell infiltration in the TME across pan-cancers, we observed a consistent result: The expression of HNRNPA2B1 is correlated with immune infiltration in all types of cancer." (PMID 39268079, 2024).
cancer (continued). "To analyze the relationship between HNRNPA2B1 and cancer progression, we calculated HNRNPA2B1 expression in different WHO cancer clinical stages in each cancer, we observed significant differences in four tumors, such as LUSC, LIHC, TGCT, and ACC." (PMID 39268079, 2024). "In most cancers, the expression of HNRNPA2B1 showed a positive correlation with immune cell infiltration." (PMID 39268079, 2024). "To further validate the correlation between HNRNPA2B1 expression and immune infiltration, we calculated the ESTIMATEScore, ImmuneScore, and StromalScore for each cancer sample, respectively." (PMID 39268079, 2024). "Second, although we conclude that HNRNPA2B1 expression is strongly associated with immune cell infiltration and prognosis of human cancers, we lack direct evidence that HNRNPA2B1 affects prognosis through its involvement in immune infiltration." (PMID 39268079, 2024). "We also evaluated the relationship between HNRNPA2B1 expression and patient prognosis in the pan-cancer dataset." (PMID 39268079, 2024). "Protein information of HNRNPA2B1 was explored by immunohistochemistry, and we found that protein levels of HNRNPA2B1 were highly expressed in several cancers." (PMID 39268079, 2024). "Our results provide a comprehensive insight into the role of HNRNPA2B1 in pan-cancer, focusing on its impact on the TME and its potential in anticancer immunotherapy, and provide a basis for developing new immunotherapy strategies." (PMID 39268079, 2024). "N6‐methyladenosine (m6A) plays pivotal roles in mRNA metabolism and hnRNPA2B1 as an m6A reader is shown to exert m6A‐dependent mRNA stabilization in cancer." (PMID 38887155, 2024). "According to previous studies, targeted HNRNPA2B1 can reduce drug resistance of cancer cells to endocrine therapy." (PMID 37072750, 2023). "Elevated HNRNPA2B1 levels in tumors accelerate pre-mRNA processing through RNA binding, suggesting a critical role for HNRNPA2B1 in cancer development." (PMID 37671941, 2023). "Previous studies have shown that overexpression of HNRNPA2B1 plays a role in endocrine resistance of cancer, enabling cancer cells to increase their vitality and obtain stem cell characteristics." (PMID 37072750, 2023). "In PAH, HNRNPA2B1 was shown to be nuclear and to stabilize its targets, while in cancer HNRNPA2B1 is known to be cytoplasmic and to destabilize its targets." (PMID 38132114, 2023). "CRNDE and hnRNPA2B1 have been reported as the two activators of MAPK signaling pathway in cancer progression." (PMID 37716979, 2023). "The correlation between HNRNPA2B1 and clinicopathological characteristics, including cancer stage, lymphatic metastasis, and Gleason score, was then investigated in the prostate tissue data from TCGA." (PMID 37215455, 2023). "The expression of hnRNPA2B1 protein was significantly higher in GC tissues compared to the para-carcinoma tissue." (PMID 37408779, 2023). "hnRNPA2B1 has been found to play a direct role in cancer development and progression by inducing EMT in various cancer types." (PMID 35279145, 2022). "hnRNPA2B1 was chosen for further investigation as it has been reported to be an EMT regulator in various cancer types." (PMID 35279145, 2022). "It is also known that hnRNPA2B1 plays a significant role in cancer progression, acting as an oncogene in the development of certain types of cancers." (PMID 35956938, 2022). "And we performed knockdown experiments for YTHDF2 and HNRNPA2B1 to reveal the biological role in the cancer cell invasion and metastasis." (PMID 35847857, 2022). "Our findings not only elucidate a mechanism of cancer-induced bone destruction, but also implicate a potential therapeutic approach for cancer patients with osteolytic bone lesions by targeting hnRNPA2B1." (PMID 36451863, 2022). "Previously, research data revealed that HNRNPA2B1 stimulates the development of cancer, such as pancreatic cancer and non-small-cell lung cancer (NSCLC)." (PMID 35529270, 2022).
cancer (continued). "Knockdown experiment results revealed that m6A regulators, YTHDF2 and HNRNPA2B1 participated in the cancer cell invasion and metastasis." (PMID 35847857, 2022). "Some studies have suggested heterogeneous nuclear ribonucleoprotein A2/B1 (HNRNPA2B1) to be a promoter in cancer development." (PMID 35529270, 2022). "Lastly, the present study facilitated the effect of HNRNPA2B1 on pan-cancers by GO and KEGG evaluations, and our results revealed that HNRNPA2B1 plays a key role in spliceosome- and cell cycle-related pathways." (PMID 35529270, 2022). "hnRNPA2B1 has two isoforms, hnRNPA2 and hnRNPB1, that regulate different gene expression patterns and phenotypes in various cancers." (PMID 35062979, 2022). "We found that high HNRNPA2B1 levels were associated with a poor prognosis of ACC, KICH, LGG, and LUAD in pan-cancer studies." (PMID 35529270, 2022). "It revealed that the phosphorylation of HNRNPA2B1 presented an increasing pattern in these cancer types." (PMID 35529270, 2022). "Transient overexpression of HNRNPA2B1 reduces the sensitivity of cancer cells to 4-hydroxytamoxifen and fulvestrant, suggesting the potential role of HNRNPA2B1 in endocrine-resistance." (PMID 35004679, 2021). "Mechanistically, the expression of RP11 is upregulated in an m6A modification-dependent manner; then, the complex composed by RP11 and HNRNPA2B1 prevents Zeb1 degradation, triggering the dissemination of cancer cells." (PMID 35004679, 2021). "We found that hnRNPA2B1 was highly expressed in various cancers in Oncomine and TCGA databases, which was consistent with what was previously reported." (PMID 34630502, 2021). "These previous studies showed that hnRNPA2B1 promotes the malignant capability of cancer cells from several aspects, in addition, hnRNPA2B1 can regulate key molecular pathways at transcriptional, post-transcriptional or even post-translational level." (PMID 34044823, 2021). "HNRNPA2B1 also acts as the m6A “reader” and very crucial in the occurrence and development of many types of cancer." (PMID 34899855, 2021). "HNRNPA2B1 plays a direct role in cancer development, cancer progression, gene expression, and signal transduction." (PMID 34476221, 2021). "Evidence has suggested HNRNPA2B1 playing a direct role in cancer initiation, development, gene expression, and signal transduction." (PMID 32322560, 2020). "Here, we found that the extract of Cotyledon orbiculata, a South African medicinal plant, had an anti-proliferative effect in cancer cells, mediated by apoptosis induced by alternative splicing of hnRNPA2B1 and BCL2L1." (PMID 33163396, 2020). "Compared with the normal subgroup, the HNRNPA2B1 expression was significantly up-regulated (P < 0.05) in cancer patients with different clinical characteristics." (PMID 33134163, 2020). "Given there are 10,459 alternative splicing events and hnRNPA2B1 interacts with multiple apoptotic and cancer genes it is probable that modulation of many of those genes collectively contribute to the reduced viability by C. orbiculata extract." (PMID 33163396, 2020). "Studies have also provided evidence that hnRNPA2B1 functions as a putative proto-oncogene in some cancers such as glioblastoma, pancreatic cancer, liver cancer, and pancreatic ductal adenocarcinoma (PDAC)." (PMID 33505405, 2020). "The upregulated expression of hnRNPA2B1 facilitates the malignant phenotypes of cancer cells by modulating many downstream target genes." (PMID 33505405, 2020). "Treatment of HCT116, OE33, and KYSE70 cancer cells with varying concentrations of C. orbiculata extract results in modulation of splicing of both hnRNPA2B1 and BCL2L1." (PMID 33163396, 2020). "hnRNPA2B1 is not only a biomarker for cancers, but also an oncogene that regulates tumor suppressors and other oncogenes in various cancers." (PMID 30755586, 2019). "HNRNPA2B1 controls the replacement splicing for the pre-mRNA of cancer-related genes, and which is up-regulated in diverse cancers." (PMID 30881302, 2019).
cancer (continued). "hnRNPA2B1 is overexpressed in cancer cell lines derived from many organs including the lung, breast, gastrointestinal tract, brain, cervix, and ovary." (PMID 30755586, 2019). "To strengthen the functional link of galectin-3 and hnRNPA2B1 in a cancer context we searched for oncogenes that were similarly affected by galectin-3 and hnRNPA2B1 knockdown." (PMID 27435226, 2016). "The scenario is different for the CBX3 and hnRNPA2B1 bi-directional promoter that results in a highly correlated expression of these two genes in the NCI-60 cancer cell panel including MCF7 and MDA-MB-231 cells." (PMID 26791953, 2016). "The RNA-binding protein hnRNPA2 (HNRNPA2B1) is upregulated in cancer, where it controls alternative pre-mRNA splicing of cancer-relevant genes." (PMID 24823909, 2014). "TRA2B or HNRNPA2B1 regulating repair of double strand breaks have elevated levels in various cancers and changed in levels by anti-cancer treatments as shown here." (PMID 23443080, 2012). "Consideration of this autoregulation will be important when examining biological situations, such as several types of cancer, where HNRNPA2B1 levels are deregulated." (PMID 20946641, 2010). "In the initial investigation, the role of HNRNPA2B1 had been verified in several human cancers." (PMID 41271615, 2025). "The hnRNPA2B1 enhanced m6A‐dependent stability of oncogene mRNAs and promoted cancer progression." (PMID 39619978, 2024). "In this study, we utilized a pan-cancer dataset to evaluate the role of HNRNPA2B1." (PMID 39268079, 2024). "This suggests that HNRNPA2B1 plays a role in the immune regulation of cancer." (PMID 39268079, 2024). "Additionally, association analysis of the PCa-associated risk loci in the cancer genome atlas program (TCGA) data unveiled genetic variations near the WTAP, HNRNPA2B1, and FTO genes as significant expression quantitative trait loci." (PMID 38610981, 2024). "To assess the impact of HNRNPA2B1 expression on cancer cell function, we evaluated the pathways by which HNRNPA2B1 may be involved in the use of gene set enrichment analysis (GSEA) in pan-cancer." (PMID 39268079, 2024). "HnRNPA2B1 is a pivotal factor in the modulation of diverse forms of cancer progression." (PMID 38626369, 2024). "This provides a new direction for research on the effect of HNRNPA2B1 on cancer progression, which could alter the modification pattern of RNA in cancer by affecting RNA modification-related genes, thereby affecting cancer progression." (PMID 39268079, 2024). "However, the role of HNRNPA2B1 in human pan-cancer development, immune microenvironment, immunotherapy, and prognosis has not been systematically analyzed so far." (PMID 39268079, 2024). "HNRNPA2B1 protein was highly expressed in cancer tissues compared with normal tissues." (PMID 37671941, 2023). "Previous reports regarding the cellular function of hnRNPA2B1 have focused on its role in cancers." (PMID 37990246, 2023). "In line with TCGA data, cancer tissues also expressed more HNRNPA2B1 than normal tissues." (PMID 37215455, 2023). "Our results show that these small molecules with high affinity to HNRNPA2B1 can play a role in endocrine resistance therapy of cancer by targeting HNRNPA2B1, but the specific mechanism and application value still need further mechanism exploration and clinical trials." (PMID 37072750, 2023). "Studies have found that hnRNPA2B1 is abnormally expressed in various cancers, indicating that it may be a potential screening biomarker for cancer." (PMID 37990246, 2023). "In HCC, PCAT6 may inhibit cancer development by regulating the expression of hnRNPA2B1 through miR-326." (PMID 37373132, 2023). "RNA-binding protein HNRNPA2B1 is involved in the transportation and posttranscriptional regulation of numerous cancer-progression-related micro RNA (miRNAs) and long noncoding RNA (lncRNA) through binding of the specific motifs GGAG/CCCU such as miR-934, Linc01232, miR100HG, H19 and RP11." (PMID 38067326, 2023).
cancer (continued). "HNRNPA2B1 may play key roles in cancer development due to its ability to accelerate pre-mRNA processing through the function of RNA binding." (PMID 36401285, 2022). "HNRNPA2B1 genetic and epigenetic changes influence cancer progression regulation." (PMID 35529270, 2022). "In this study, the HNRNPA2B1 levels were explored in pan-cancer." (PMID 35529270, 2022). "This systematic study highlighted the role of HNRNPA2B1 in pan-cancer progression." (PMID 35529270, 2022). "Moreover, the hnRNPA2B1 expression level varied in different cancer types, resulting in these divergent findings in cellular uptake studies." (PMID 36015303, 2022). "RAN and HNRNPA2B1 showed differential expression in most cancers." (PMID 35151325, 2022). "With all these correlations between hnRNPA2B1 and cancer, this gene may have a high predictive value, as well as another heterogeneous nuclear ribonucleoprotein, hnRNPC." (PMID 36051357, 2022). "This study reports that HNRNPA2B1 may affect various mechanisms that contribute to cancer development." (PMID 35529270, 2022). "We also evaluated gene expression levels, survival rates, methylation status, changes in protein phosphorylation, immune cell infiltration, and related signaling pathways to see if HNRNPA2B1 could play a role in pan-cancer prognosis." (PMID 35529270, 2022). "The target cancer cell MDA-MB-231 showed strong expression of hnRNPA2B1 at 36/38 kDa." (PMID 36015303, 2022). "As a result, HNRNPA2B1 may function as a potential promoter and biomarker in the development and prognosis of cancer." (PMID 35529270, 2022). "HNRNPA2B1 participates in multiple biological processes in many diseases, especially cancers." (PMID 36401285, 2022). "The presence of HNRNPA2B1 in normal lung and cancer samples was investigated." (PMID 35529270, 2022). "Similarly, by analyzing the mutation annotation files of the TCGA cohort, the results showed that HNRNPA2B1 has a close correlation with TMB in multiple types of cancer, particularly ACC." (PMID 33746977, 2021). "The role of HNRNPA2B1 in cancer has recently garnered increasing attention." (PMID 33746977, 2021). "The hsa-miR-195-5p and hsa-miR-326 regulating HNRNPA2B1 were found in more than one cancer type." (PMID 33718187, 2021). "Additionally, splicing factor heterogeneous nuclear ribonucleoprotein A2B1 (hnRNPA2B1) significantly promotes malignant behaviors and tumorigenesis of various cancers." (PMID 34295828, 2021). "Moreover, Spearman's correlation was used to show the relationship between HNRNPA2B1 and immune-related mRNAs in 33 cancer types." (PMID 33746977, 2021). "HNRNPA2B1 showed widespread copy number amplification across various cancer types." (PMID 32915499, 2020). "Furthermore, by treating cancer cells with Act-D to terminate transcription, our results demonstrated that silencing of hnRNPA2B1 significantly decrease the stability of Raf-1 in HCT116 and SW480 cells." (PMID 32698890, 2020). "HNRNPA2B1 has been reported to be a RNA-binding protein involved in different cancer progression." (PMID 33134163, 2020). "Previous studies have already investigated the prognostic role of HNRNPA2B1 in many cancer types." (PMID 32485038, 2020). "In addition, the copy number variations of hnRNP genes were also investigated across different cancer types: HNRNPA2B1 gene showed widespread copy number amplification across various cancer types whereas almost no CNV was detected in LAML." (PMID 32915499, 2020). "However, from our results, among MO-460 targets, hnRNPA2B1 seems to be valuable as an anti-cancer target on HIF-1α inhibition." (PMID 30755586, 2019). "Of the hnRNPs, hnRNPA2 and splice variants (hnRNPs B1/A2b/B1b, hereafter referred to collectively as hnRNPA2), encoded by the HNRNPA2B1 gene, have generated significant interest due upregulation of expression in a number of cancers." (PMID 24823909, 2014).